EGF (epidermal growth factor)
Diseases named in the same sentence as EGF in open-access papers (continued):
Sharing a sentence is not in itself a finding about the gene and the disease.
pancreatic cancer (continued). "In agreement with this possibility, Deltazinone 1 required a much higher concentration (20 μM) to modestly inhibit EGF-induced S6 phosphorylation in a human pancreatic adenocarcinoma cell line and was ineffective in another pancreatic cancer cell line tested." (PMID 35814251, 2022). "MiR-21expression is closely associated with the regulation of the epidermal growth factor (EGF) signaling pathway, while it induces EGF-related pancreatic cancer cell proliferation, deregulates the cell cycle function, and suppresses apoptosis." (PMID 36292753, 2022). "Common pathways that have a role in pancreatic cancer were taken into consideration: the EGF, FAK, WNT/β-catenin, PI3K/AKT, ERK/MAPK, and the tumor microenvironment pathways." (PMID 36009530, 2022). "High-glucose culture of pancreatic cancer cell lines increases the expression of EGF, which then activates EGFR." (PMID 35222283, 2022). "Thiosemicarbazones have been demonstrated to inhibit the expression and activation of the ErbB family of receptors in response to EGF in pancreatic carcinoma cells in vitro and in vivo." (PMID 36160437, 2022). "Epidermal growth factor (EGF) enhances the invasive capacity of PANC-1 human pancreatic cancer cells by inducing secretion of the collagenase MMP-2." (PMID 33754031, 2021). "Using pancreatic cancer cells, it was shown that curcumin reduced hyperglycemia-driven EGF-induced metastatic abilities." (PMID 34867402, 2021). "In conclusion, KLK8 overexpression exerts pro-proliferation and anti-apoptotic functions in pancreatic cancer cells via EGF signaling-dependent activation of PI3K/Akt/mTOR pathway." (PMID 34395235, 2021). "In summary, our findings indicate that KLK8 overexpression exerts pro-proliferation and anti-apoptotic functions in pancreatic cancer cells via EGF signaling-dependent activation of PI3K/Akt/mTOR pathway." (PMID 34395235, 2021). "In a murine model for pancreatic cancer, the authors attributed the observed increased EGF secretion of organoid tumor cultures to ligand shedding, mediated by NRF2-dependent stimulation of the ADAM10 metalloprotease." (PMID 33916908, 2021). "EGF/EGFR signaling pathway has been known to promote the proliferation of pancreatic cancers via activating PI3K/AKT pathway." (PMID 34395235, 2021). "In summary, our present studies indicate that IATL inhibits pancreatic carcinoma by inhibition of the EGF- AMPK-Skp2-Akt signal pathway." (PMID 33661942, 2021). "For example, the receptor tyrosine kinase (RTK) ligand EGF stimulated a transient calcium response and activated CaCC in the pancreatic cancer cell line AsPC-1, which was inhibited by ANO1 knockdown." (PMID 33250781, 2020). "Our previous study showed that calreticulin (CRT) promoted EGF-induced epithelial-mesenchymal transition (EMT) in pancreatic cancer (PC) via Integrin/EGFR-ERK/MAPK signaling." (PMID 33028359, 2020). "The results suggest that the autocrine loop involving EGF signaling is a key interaction modulator between pancreatic cancer and stellate cells." (PMID 32696951, 2020). "ANO1 is also required for EGF-induced store-operated calcium entry (SOCE) in pancreatic cancer cells; however, in both latter studies, the precise mechanism by which ANO controls Ca2+ signaling was not determined." (PMID 33250781, 2020). "Epidermal growth factor (EGF) can also induce EMT in pancreatic cancer cells via stimulating the integrin/EGFR-ERK/MAPK signaling pathway." (PMID 31126310, 2019). "Consistently, direct activation of either ErbB3 or EGFR signaling with specific ligands (NRG-1 and EGF, respectively) also resulted in significant abrogation of anti-pancreatic cancer activity of VPA." (PMID 30961642, 2019). "DTEGF13 is a bispecific immunotoxin consisting of DT390 fused to EGF and IL-13, made to target a range of solid tumors including glioblastoma, prostate, and pancreatic cancers, which overexpress receptors for both EGF and IL-13." (PMID 31681205, 2019).
pancreatic cancer (continued). "We similarly profiled CM from primary pancreatic tumor associated stromal (TAS) cells, which secreted very high levels of EGF (4337 pg/mL) and MCP-1/CCL2 (4,951 pg/mL), moderate levels of IL-8 (70.94 pg/mL), and low levels of GRO (18.65 pg/mL)." (PMID 31769424, 2019). "EGF stimulation of pancreatic carcinoma cells led to invasion and metastasis that was blocked by antagonists of ITG." (PMID 31182680, 2019). "Our results showed that miR-21 played important roles in EGF-induced pancreatic cancer cell proliferation." (PMID 30464258, 2018). "Overexpression of miR-21 under EGF stimulation was also confirmed in other pancreatic cancer cell lines." (PMID 30464258, 2018). "It has also been shown that EGFR and MUC1 will accumulate in the perinuclear space in pancreatic cancer cells after exposure to EGF stimuli, similar to our current findings." (PMID 29464085, 2018). "In this study, we demonstrate that EGF can induce the expression of miR-21, which enhances EGF-induced pancreatic cancer cell survival by targeting the MAPK/ERK and PI3K/AKT signaling pathways." (PMID 30464258, 2018). "Although both EGFR signaling and miRNAs can profoundly influence pancreatic cancer cell behavior, the role of miRNAs in EGF-mediated phenotypes is poorly defined." (PMID 30464258, 2018). "EGF treatment contributed to NF-κB activity in human proximal tubule cells and in pancreatic cancer." (PMID 30034618, 2018). "Consistently, we detected rapid phosphorylation of PIPKIγ at Y639 induced by EGF treatment in pancreatic cancer cells." (PMID 28388589, 2017). "Previous studies have demonstrated higher EGFR and EGF expression in pancreatic cancer tissue compared to normal pancreatic tissue." (PMID 27788491, 2016). "Consistent with pro-oncogenic role, it is upregulated by Her2 oncogene and by epidermal growth factor and repressed by Ink4A in breast and pancreatic cancer." (PMID 26161255, 2015). "Glypican 1 expression is upregulated in pancreatic cancer cells and surrounding fibroblasts, and the mitogenic response of pancreatic cancer cells to bFGF and HB-epidermal growth factor is abrogated by antisense attenuation of this HS-PG." (PMID 26448753, 2015). "RGS16 inhibited EGF induced migration of BxPC-3 and AsPC-1 cells, we further investigated if RGS16 can inhibit EGF induced invasion of these pancreatic cancer cells using matrigel invasion chambers." (PMID 25568667, 2014). "In sum, this set of experiments for the first time shows that EGF signaling relies on AR/Src complex in colon and pancreatic cancer cells." (PMID 24130806, 2013). "A prognostic study in Chinese patients with pancreatic cancer indicated that the median survival rates were 17.2 months and 9.7 months for the EGF (-) EGFR (-) group and EGF (+) EGFR (+) group, respectively." (PMID 24130758, 2013). "It is well known that EGF plays an important role in pancreatic cancer progression and EGF and its ligand over-expression have been frequently observed in pancreatic cancer." (PMID 22244109, 2012). "Several studies have demonstrated that TGF-β alone or in combination with other growth factors such as EGF plays vital roles in mediating EMT in many malignant tumors including pancreatic cancer." (PMID 23300530, 2012). "In this model, FG human pancreatic carcinoma cells are stimulated with a 15 minute treatment of EGF or vehicle in vitro and then implanted on the CAM of 10 day-old chick embryos and allowed to spontaneously metastasize to the lungs." (PMID 22586492, 2012). "A number of growth factors and their receptors have been shown to play an important role in pancreatic cancer, including the epidermal growth factor (EGF) family." (PMID 24212772, 2011). "Including a panel of seven CAC, the results show that certain CAC such as VEGF, PDGF-AA, Ang-1 and EGF are differentially expressed in patients with pancreatic cancer compared to healthy subjects." (PMID 21729304, 2011).
pancreatic cancer (continued). "For example, blockade of integrin αvβ5 reverses the EGF-stimulated invasion and metastasis in pancreatic cancer cells." (PMID 22053213, 2011). "We also demonstrated that Y27632 suppressed the phosphorylation of both molecules, thus suggesting that the phosphorylation of cofilin and MLC by EGF occurs through ROCK in pancreatic cancer cells." (PMID 21722395, 2011). "In our work, ΔNp63α dramatically potentiated pancreatic cancer cell motility and invasive abilities in the presence of EGF." (PMID 22053213, 2011). "VEGF (p < 0.0001), PDGF-AA (p < 0.0001), Ang-1 (p = 0.002) and EGF (p < 0.0001) were differentially expressed in patients with pancreatic cancer compared to healthy controls." (PMID 21729304, 2011). "In late stage pancreatic cancer, specific serum growth factor levels are overexpressed such as EGF, VEGF, FGF and PDGF." (PMID 24212642, 2011). "Engagement of these growth factors (VEGF, IGF, PDGF, FGF, EGF, TGFβ) and their signaling cascades at different stages of pancreatitis and pancreatic carcinoma development appear to be crucial for the progression of these diseases." (PMID 24212642, 2011). "Our result shows that both LY294002 and rapamycin inhibit the up-regulation effect of HCCR-1 by EGF, suggesting that EGF-induced HCCR-1 expression is mediated by PI3K/mTOR signaling in pancreatic cancer." (PMID 20423485, 2010). "It suggests that HCCR-1 is one of the down-stream components of the EGF-triggered PI3K/Akt/mTOR signaling which plays a pivotal role in the pancreatic cancer tumorigenesis." (PMID 20423485, 2010). "Here in this study, we demonstrate that HCCR-1 is responsible for pancreatic cancer via EGF mediated-PI3K/Akt/mTOR signaling pathway." (PMID 20423485, 2010). "The aim of this study was to investigate the effect of epidermal growth factor on the expression of HCCR in pancreatic cancer cells, and to explore if PI3K/Akt/mTOR signaling pathway mediated this expression." (PMID 20423485, 2010). "In one report, strong TGFα immunoreactivity was found in 95% of pancreatic tumors, whereas EGF immunoreactivity was observed in only 12% of the tumors." (PMID 16822304, 2006). "Because EGF and related erbB receptor ligands have been implicated in cellular adhesion and migration, we set out to investigate the role of EGF in adhesion and invasion in a pancreatic cancer cell line." (PMID 15801978, 2005). "We examined the effects of SS-14 and its analogue RC-160 on the in vitro growth of two human pancreatic cancer cell lines MiaPaCa-2 and Panc-1 stimulated with epidermal growth factor (EGF) or insulin-like growth factor 1 (IGF-1)." (PMID 1355659, 1992). "In contrast RC-160 did inhibit the EGF-stimulated growth of a rat pancreatic cancer cell line AR42J." (PMID 1355659, 1992). "Plasma EGF-TGF-alpha levels increased significantly at day 5 of treatment only in the pancreatic cancer patients." (PMID 1977468, 1990). "In pancreatic cancer treatment, EGF is also used to enhance the targeted ability of liposomes." (PMID 39891180, 2025). "Alterations or dysregulation of the EGF gene or its signaling pathway can be associated with various diseases, including cancers viz. colorectal cancer, non-small cell lung cancer (NSCLC), prostate and pancreatic cancers." (PMID 40226632, 2025). "Wei Li and team revealed that curcumin effectively suppresses the proliferation and invasive capabilities of pancreatic cancer cells induced by high glucose levels and EGF, primarily through the inhibition of the ERK and Akt pathways and by downregulating EGFR activation." (PMID 38474160, 2024). "Based on data that has attributed cellular functions to fibroblast proliferation in other tissues, we investigated a panel of ten central regulators of cell proliferation (c-Myc, Cyclin D1, Cyclin E1, FGF2, FGFR2, EGFR, EGF, FGF1, FGFR1 and VEGFA) in pancreatic cancer-associated fibroblasts (CAFs)." (PMID 38678032, 2024).
pancreatic cancer (continued). "Although miR-338-5p/EGFR axis has been shown to inhibit multidrug resistance and cell growth in hepatocellular carcinoma, the results of the present study indicate that miR-338-5p/EGFR axis inhibits the metastasis of pancreatic cancer partially dependent on EGF." (PMID 33937024, 2021). "Overexpression of KLK8 might promote proliferation and inhibit apoptosis via epidermal growth factor (EGF) signaling-dependent activation of PI3K/Akt/mTOR pathway in pancreatic cancer cells." (PMID 34395235, 2021). "In the same study, calreticulin was found to be co-localized with pEGFR1173, fibronectin, and integrin β1, while being co-immunoprecipitated with fibronectin, integrin β1, and c-Myc, which suggests the direct involvement of calreticulin in the regulation of EGF-induced EMT in pancreatic tumors." (PMID 32268506, 2020). "Here, we demonstrated that miR-21 expression was induced by EGF in pancreatic cancer cells." (PMID 30464258, 2018). "Then, we conducted a series of experiments to assess whether Spry2 alone was sufficient to modulate EGF signaling in pancreatic cancer cells." (PMID 30464258, 2018). "We investigated whether chronic exposure to EGF modifies in a SMAD4-dependent manner pancreatic cancer cell signalling, proliferation and invasion in response to EGF, TGFβ1 and S100A8/A9." (PMID 27655713, 2016). "In accordance with our findings, a recent report demonstrates that oncogenic KRAS requires EGF stimulation for enhanced activity in pancreatic cancer cells: EGF induced a prolonged activity of oncogenic KRAS, whereas only transient effects are seen in cells with wild type KRAS." (PMID 25992771, 2015). "We speculate that TRPM7 and its regulated Mg2+ homeostasis modulate epidermal growth factor (EGF)-induced signaling pathways, resulting in cellular proliferation, survival, and migration/invasion of pancreatic cancer cells." (PMID 25770184, 2015). "Human pancreatic cancer cell lines established at our department were cultured in CSC-inducing media containing epidermal growth factor (EGF), basic fibroblast growth factor (bFGF), leukemia inhibitory factor (LIF), neural cell survivor factor-1 (NSF-1), and N-acetylcysteine." (PMID 25118635, 2014). "EGF was used to stimulate cell migration because EGFR is overexpressed in pancreatic cancer and is linked with development, invasion, and decreased survival in pancreatic cancer." (PMID 25568667, 2014). "In conclusion, although further studies are required to fully address the molecular mechanism of HCCR-1 on the pancreatic tumorigenesis, our result provides the insight on the role of HCCR-1 and its involvement in the pancreatic cancer via the EGF-triggered PI3K/Akt/mTOR pathway." (PMID 20423485, 2010). "EGF-induced HCCR-1 over-expression is mediated by PI3K/AKT/mTOR signaling which plays a pivotal role in pancreatic tumor progression, suggesting that HCCR-1 could be a potential target for cancer therapeutics." (PMID 20423485, 2010). "In human pancreatic cancer cells, epidermal growth factor (EGF) induces the secretion and activation of MMP-2 through an intracellular signaling pathway that involves PI3K- and Src-dependent activation of Rac1, which, in turn, is responsible for the NOX-mediated ROS production." (PMID 24281116, 2010). "EGF stimulation on PANC-1 cells was commenced to determine whether and how EGF regulates the expression of the HCCR-1 crucial for the pancreatic cancer growth and survival." (PMID 20423485, 2010). "Interestingly, the over-expression of HCCR-1 found in most of pancreatic cancers was triggered by EGF signaling which has been already known to regulate the pancreatic cancer development." (PMID 20423485, 2010).
pancreatic cancer (continued). "The co-expression of these EGF families of ligands and receptor tyrosine kinases suggests that an autocrine mechanism is operative in pancreatic cancer, thereby allowing autonomous activation of signalling pathways that manifests as an aggressive tumor phenotype." (PMID 15801978, 2005). "Further experiments comparing these and other pancreatic cancer cell lines would need to be performed to determine whether these differential responses to EGF and HRG-α hold true." (PMID 15801978, 2005). "We therefore asked whether the adhesion response to EGF on collagen I was a property shared between these two pancreatic cancer cell lines." (PMID 15801978, 2005). "Mir-21 could accelerate epidermal growth factor (EGF) induced pancreatic cancer cell proliferation." (PMID 37372974, 2023). "For example, epidermal growth factor expression and epidermal growth factor receptor transactivation may be induced by high glucose, which can contribute to promoting cell proliferation in pancreatic cancer." (PMID 36937438, 2023). "Moreover, EGF treatment could rescue the invasion and migration ability of pancreatic cancer cells, which was inhibited in CD44V3 knockdown pancreatic cancer cells." (PMID 36292918, 2022). "We hypothesize that targeting SIRT7 might be beneficial for treating EGF signaling-dependent cancers, e.g., triple-negative breast cancers with increased EGFR expression and activity, colorectal and pancreatic cancers that harbor Ras mutations and NSCLCs with EGFR mutations." (PMID 34433808, 2021). "The aim of the present study was to improve our understanding of the way in which EGF governs the pancreatic cancer cell response to relevant stromal derived molecules, TGFβ1 and S100A8/A9, while also investigating whether SMAD4 participates in this complex scenario." (PMID 27655713, 2016). "Indeed, as shown in pancreatic cancer cells, EGF stimulation leads to tyrosine phosphorylation of Vav1, followed by the activation of a Rac1/Pak1/NF-κB signaling pathway resulting in an increase in cyclin D1 which leads to enhanced pancreatic tumor cell proliferation." (PMID 26353933, 2015). "Hbegf-Egfr/Erbb2 is one of the main contributors to EGF signaling, and EGFR-activated myo-CAFs can promote pancreatic cancer metastasis." (PMID 40538442, 2025). "The top enriched pathways include AGE-RAGE, epidermal growth factor (EGFR), and VEGF, which are highly expressed in pancreatic cancer." (PMID 40573291, 2025). "The liposomal nanocarrier was tested with human pancreatic cancer cell lines that express EGFR, and the EGF-decorated liposome enhanced the antitumor activity of curcumin in pancreatic cancer chemotherapy." (PMID 39891180, 2025). "Curcumin suppressed the EGF/EGFR signaling pathway, which in turn prevented hyperglycemia-driven EGF-induced pancreatic cancer from migrating and invading by downregulating the ERK and Akt signaling molecules." (PMID 39770516, 2024). "In pancreatic cancer, angulin-1/LSR also contributes to the epithelial barrier and malignancy via the growth factors EGF and TGF-β." (PMID 36961882, 2023). "In pancreatic cancer, angulin-1/LSR contributes to the epithelial barrier and malignancy via the growth factors EGF and TGF-β." (PMID 36961882, 2023). "Interestingly, these alterations also occur in pancreatic cancer, where they have been associated with disease progression and metastasis through the activation of oncogenic pathways via the interaction between aberrant MUC16 isoforms and epidermal growth factor (EGF) receptors." (PMID 35884534, 2022). "Because ARL4C expression is induced by Wnt and EGF signaling, it is reasonable that ARL4C would be expressed in a β-catenin- and RAS-dependent manner in pancreatic cancer cells." (PMID 34590580, 2021). "There are several mitogenic growth factors and their ligands, which are overexpressed in pancreatic cancer, namely: EGF and EGFR (receptor of EGF), multiple EGFR binding ligands; FGF and FGFR; IGF and its receptor (IGFR); PDGF; VEGF." (PMID 33918146, 2021).